ACSL3 (acyl-CoA synthetase long chain family member 3)
Diseases named in the same sentence as ACSL3 in open-access papers (continued):
Sharing a sentence is not in itself a finding about the gene and the disease.
breast cancer (19 papers, 2015 to 2025). A primary or metastatic malignant neoplasm involving the breast. "The complete deletion of ACSL3 has been linked to an elevated risk of breast cancer recurrence and distant metastasis in triple-negative breast cancer following chemotherapy." (PMID 40932861, 2025). "Interestingly, for both prostate and breast cancers increased ACSL3 is also associated with particular tumour subtypes." (PMID 32286604, 2020). "Suppression of lipogenesis and ACSL3 expression in dormant breast cancer cells shifts the lipid profile from being rich in MUFA to one enriched in PUFA." (PMID 40919170, 2025). "In breast cancer (BC) cells overexpression of ACSL3 reduces FFA levels, whereas its downregulation increases FFA levels." (PMID 41288931, 2025). "In breast cancer, dormant disseminated tumor cells (DTCs) are characterized by elevated de novo lipogenesis and overexpression of ACSL3." (PMID 40919170, 2025). "Further, adipocytes in breast cancer rely on the fatty acid synthase ACSL3(acyl-CoA synthetase long-chain family member 3) to release MUFA (oleic acid), enabling cancer to resist ferroptosis." (PMID 38800384, 2024). "Another study on different types of breast cancers revealed that ACSL3 and ACSL4 were highly, but in a differential manner, expressed in a group of leiomyosarcomas, fibrosarcoma, and rhabdomyosarcomas." (PMID 36497375, 2022). "Taken together, mammary adipocytes can protect breast cancer cells from ferroptosis through oleic acid in the presence of ACSL3." (PMID 35659320, 2022). "A reduction in ACSL3, FASN and SCD mRNA expression has been observed across the different breast cancer cell lines and linked with fatty acid metabolism-associated genes." (PMID 34944852, 2021). "Given that ACSL4 has been found necessary for ferroptosis in breast cancer cells, we also report our findings regarding the subcellular targeting of endogenously expressed ACSL3 and ACSL4 in MCF7 breast cancer cells." (PMID 29450800, 2018). "ACSL4 mRNA is significantly overexpressed in TNBC and basal-like breast cancers, while ACSL3 mRNA expression predominates in RPBC and luminal and HER2-enriched subtypes." (PMID 28412757, 2017). "Notably, all the FA metabolic genes ELOVL6, ACSL1, ACSL3, ACSL4, ACDSB and ACAT1 showed significant positive correlation with NAT10 suggesting that overexpression of NAT10 in breast cancer patients is associated with FA metabolism." (PMID 36149760, 2022). "However, downregulation of ACSL3 also inhibited the proliferation, migration, and invasion of breast cancer cell lines, alternatively suggesting instead a pro-tumorigenic role." (PMID 35448537, 2022). "Homozygous deletion of ACSL3 in Korean TNBC patients, discovered via targeted exome sequencing, found the deletion to be associated with the increased risk of relapse and promoted distant metastasis in breast cancer patients, following adjunct chemotherapy treatment." (PMID 35448537, 2022). "Two ACSL3 transcripts were observed in the NHBE cells and have also been detected in mammary carcinoma cells as well as hamster liver and rat pancreatic islets." (PMID 38539505, 2024). "The intracellular localisations of endogenously expressed ACSL3 and ACSL4 were further investigated by detailed subcellular fractionation analyses of HT1080 fibrosarcoma and MCF-7 breast cancer cells." (PMID 29450800, 2018). "Breast cancer cells treated with etomoxir to inhibit CPT1A resulted in cell death, while in vivo, mutant KRAS lung tumours were dependent on ACSL3-dependent FAO for tumour initiation and progression." (PMID 30092766, 2018). "Analysis of differential expression levels highlighted CLDND1, PLEKHA2, ACSL3, SLC30A9, MSN, CALM3 and PRKAR1A as potential regulators of breast cancer cell survival since they were affected by PKCδ siRNA in all cell lines." (PMID 26083392, 2015).
breast cancer (continued). "Mono-unsaturated Fatty Acid (MUFA) regulates breast cancer cells by binding with acyl-CoA synthetase long chain family member 3 (ACSL3) to phospholipids, and it is confirmed that the regulation of ferroptosis in breast cancer by adipocytes and exogenous MUFA is dependent on ACSL3." (PMID 36467032, 2022). "Quadruple-negative breast cancer tissues, on the other hand, have higher expression of ACSL4 than their healthy counterparts, whereas ER- breast cancer overexpresses ACSL1, ACSL3, ACSL4 and ACSL4." (PMID 35448537, 2022).
prostate carcinoma (17 papers, 2008 to 2025). A carcinoma that arises from epithelial cells of the prostate gland. "ACSL4, as well as ACSL3, which is an enzyme that converts fatty acids to acyl-CoA, is also involved in the loss of androgen sensitivity and acquisition of castration resistance, leading to cancer growth and invasion in prostate cancer." (PMID 33123488, 2020). "Interestingly, ACSL3 overexpression leads to the upregulation of enzymes involved in steroids synthesis, one of the mechanisms underlying the development of castration-resistant prostate cancer." (PMID 31344914, 2019). "ACSL3, located at 2q36.3, comprises 20 exons and harbors hormone-responsive elements, correlating with its role in prostate cancer progression." (PMID 40932861, 2025). "The expression of ACSL3 increased in prostate cancer cells, which promoted the growth of CRPC by promoting the synthesis of dehydroepiandrosterone and preventing the catabolism of active androgen." (PMID 38743344, 2024). "Of the genes that are jointly regulated by OCT1 and the AR in prostate cancer, acyl-CoA synthetase long-chain family member 3 (ACSL3) is the mostly highly differentially expressed." (PMID 33134178, 2020). "ACSL3 is expressed in both androgen-sensitive and castration-resistant prostate cancer, but in the latter its expression is dramatically higher." (PMID 31344914, 2019). "We selected three R1881-regulated genes to be analyzed by quantitative PCR on normal prostate and prostate carcinoma samples obtained in our institute: ACSL3, MCCC2 and ENDOD1." (PMID 21829708, 2011). "As for ACSL3, it has been shown that the antiproliferative effect of Vitamin D in prostate cancer cells is mediated by ACSL3 overexpression, an effect that is blocked by Triacsin C." (PMID 21085606, 2010). "Among these, an upregulation of ACSL3 predicts a worse prognosis for prostate cancer patients." (PMID 40932861, 2025). "ACSL3, an androgen-responsive gene involved in the generation of fatty acyl-CoA esters, could promote intratumoral steroidogenesis in prostate cancer cells." (PMID 33519933, 2021). "Moreover, increased fatty acid oxidation has also been suggested as a source of energy, along with increased steroidogenesis by upregulation of Acyl-CoA synthetase long-chain family member (ACSL) 3 (ACSL3) in prostate cancer." (PMID 33123488, 2020). "Moreover, in a prostate cancer cell model, ACSL3 overexpression conferred resistance to tunicamycin-sensitive cancer cells." (PMID 31344914, 2019). "In the castration-resistant prostate cancer context, ACSL3 promotes androgen synthesis through adrenal androgen dehydroepiandrosterone sulfate as a substrate, suggesting that ACSL3 may select for castration-resistant cancer cell populations." (PMID 31344914, 2019). "ACSL3 is an androgen receptor (AR)-stimulated gene and was recently identified in formalin-fixed prostate cancer tissue as a new 5′ translocation partner of ETS variant 1 (ETV1), an important gene in driving prostate cancer progression." (PMID 29156692, 2017). "Finally, ACSL3 is able to drive steroidogenesis in castration-resistant prostatic cancer." (PMID 31344914, 2019). "Thus, in this context, ACSL3 may be an attractive therapeutic target to prevent prostate cancer relapse." (PMID 31344914, 2019). "Thus, it would be interesting to assess whether the increased ACSL3 expression is concomitant to the cessation of the efficacy of the androgen-deprivation treatment and the development of castration-resistant prostate cancer." (PMID 31344914, 2019). "Studies demonstrated that overexpression of ACSL3 was detected in various malignancies such as hepatoma, prostate cancer, and NSCLC, revealing ACSL3 as a promising protective factor of prognosis in patients with cancer." (PMID 39323079, 2024).
prostate carcinoma (continued). "In prostate cancer, androgen receptors synergistically regulate the expression of ACSL3 and ACSL4, and knocking out ACSL4 inhibits the proliferation, migration, invasion, and xenograft growth of androgen receptor dependent prostate cancer cells." (PMID 37305043, 2023). "Furthermore, a comprehensive analysis of OCT1 signals revealed that Acyl-CoA Synthetase Long-Chain Family Member 3 (ACSL3) was the most highly expressed gene regulated by both AR and OCT1 in hormone-responsive prostate cancer cells (LNCaP cells)." (PMID 38698344, 2024). "ACSL3 was found to be overexpressed in prostate cancer and estrogen receptor‐negative breast cancer." (PMID 33030783, 2020). "In contrast, there is a lower ACSL3 expression in prostate cancer tissue compared to that in normal tissue." (PMID 27171439, 2016). "In order to identify androgen-regulated genes that could possibly be used in the diagnosis/prognosis of prostate cancer, we selected from our 107-gene signature three androgen-regulated genes: MCCC2, ENDOD1 and ACSL3." (PMID 21829708, 2011). "Expression of ACSL3 was also elevated in a panel of ‘androgen-sensitive’ (LAPC-4, LNCaP, MDA PCa2a, MDA PCa2b, and 22Rv1) versus ‘androgen-insensitive’ (PPC1, PC3, and DU145) prostate cancer cell lines." (PMID 18594527, 2008).
asthma (14 papers, 2009 to 2024). "Prenatal exposure of PAH was associated with increased methylation status of ACSL3 gene, which in turn has been associated with increased incidences of development of childhood asthma." (PMID 27293973, 2016). "For example, hypermethylation of the acyl-CoA synthetase long-chain family member 3 (ACSL3) gene implicated in asthma pathogenesis has been indicated in umbilical cord white blood cells of neonates who were prenatally exposed to PAHs." (PMID 26366233, 2015). "Our group previously reported that in cord blood samples methylation of a CGI in ACSL3, a gene involved in fatty acid metabolism, was associated with maternal exposure to PAHs and with reported asthma in children through 5 years of age." (PMID 22562770, 2012). "In a cohort of children living in New York City, exposure to PAHs was associated with DNA methylation in the ACSL3 gene, a gene associated with asthma symptoms in children." (PMID 22591701, 2012). "However, the recent reports on ACSL3 as a potential epigenetic marker for prediction of PAH associated asthma provide the first yet important step in this research domain." (PMID 27293973, 2016). "ACSL3 has been shown to be associated with asthma susceptibility in specific populations." (PMID 24450480, 2014). "Interestingly, ACSL3 is located in close proximity to 2q36, an asthma susceptibility locus found in Hutterite and Puerto Rican populations." (PMID 22562770, 2012). "As for allergic manifestations, methylation of the ACSL3 5’-CGI has been found to correlate with asthma status in children and has been reported to increase in an allergen-induced airway hyperreactivity model in mice." (PMID 38585273, 2024). "Moreover, methylation of the ACSL3 5′-CGI was significantly associated with maternal airborne polycyclic aromatic hydrocarbon exposure above 2.41 ng/m3 in umbilical cord white blood cells potentially related to the development of traffic-related air pollution exposure asthma." (PMID 32047643, 2019). "Prenatal exposure to traffic-related PAHs was also shown to be linked with hypermethylation of the acyl-CoA synthetase long-chain family member 3 (ACSL3) gene, which impacts asthma pathogenesis in umbilical cord blood of newborns." (PMID 31097039, 2019). "Maternal exposure to PAH is associated with DNA methylation changes in the acyl-CoA synthetase long-chain family member 3 (ACSL3) gene in cord blood cells of children and is also associated with higher risk of developing asthma." (PMID 27777592, 2016). "Further mechanistic studies are needed to delineate out the role of ACSL3 in the development of asthma, especially childhood asthma." (PMID 27293973, 2016). "ACSL3, a gene that encodes a key enzyme in fatty acid metabolism, was significantly associated with maternal PAH exposure and with reported childhood asthma through 5 years of age." (PMID 22562770, 2012). "DNA methylation of the Foxp3, ACSL3, and ARG2 loci are associated with impaired regulatory T-cell function, increased asthma morbidity, and exhaled nitric oxide production, respectively." (PMID 22740325, 2012). "Children living in more highly polluted communities had changes in DNA methylation of FOXP3 and ACSL3 genes, both important in asthma morbidity and symptoms in children." (PMID 22591701, 2012). "Methylation of the ACSL3 5′CGI was positively and significantly associated with asthma classification." (PMID 19221603, 2009). "Further mechanistic studies in in vitro and in vivo experimental models are needed to decipher the role of ACSL3 in childhood asthma." (PMID 19221603, 2009). "The current report of ACSL3 as a candidate biomarker of PAH exposure and a putative predictor of PAH-associated childhood asthma represents an important first step in this area of research." (PMID 19221603, 2009).
asthma (continued). "Previously, higher prenatal PAH exposure was associated with increased DNA methylation of interferon γ and acyl-CoA synthetase long-chain family member 3 (ACSL3) in human cord blood; the latter was associated with a greater odds of reported asthma by age 5 years." (PMID 25347678, 2014). "Methylation of a 5′-CpG island (CGI) in acyl-CoA synthetase long-chain family member 3 (ACSL3) was found to be positively and significantly associated with the level of maternal PAH exposure and with a parental report of asthma symptoms prior to age 5 in this exploratory study." (PMID 19221603, 2009). "This well though out, step-wise approach allowed us to identify a candidate to be tested in the 56-sample study to determine whether methylation of the ACSL3 5′CGI could be a stand alone biomarker for PAH exposure and/or PAH-associated childhood asthma." (PMID 19221603, 2009). "In this exploratory study, we have identified ACSL3 as a candidate biomarker/gene whose 5′-CGI methylation status appears to be related to transplacental PAH exposure and further associated with PAH-associated asthma." (PMID 19221603, 2009). "Thus, ACSL3 may be the first potential surrogate endpoint for environmentally related childhood asthma." (PMID 19221603, 2009). "Methylation of the ACSL3 5′-CGI was found to be significantly associated with maternal airborne PAH exposure exceeding 2.41 ng/m3 (OR = 13.8; p<0.001; sensitivity = 75%; specificity = 82%) and with a parental report of asthma symptoms in children prior to age 5 (OR = 3.9; p<0.05)." (PMID 19221603, 2009). "The aim of this study was to compare the mRNA expression patterns of Interleukin (IL)-4, interferon (IFN)-γ and Acyl Co A long chain 3 (ACSL3) in peripheral blood leukocytes of children with and without asthma." (PMID 24450480, 2014). "We focused on the expression of IL-4, IFN-γ and ACSL3 mRNA in peripheral blood mononuclear cells (PBMC) of Saudi children with and without asthma and sought possible associations between cytokines and PAH levels." (PMID 24450480, 2014). "In this study, we investigated the expression of IL-4, IFN-γ and ACSL3 mRNA in PBMCs of the children with and without asthma and speculated that cytokine expression in PBMCs may provide useful information regarding the allergic disease." (PMID 24450480, 2014). "Thus, if validated, methylated ACSL3 5′CGI in UCWBC DNA may be a surrogate endpoint for transplacental PAH exposure and/or a potential biomarker for environmentally-related asthma." (PMID 19221603, 2009). "ACSL3 was chosen for subsequent assessment of the relationships between prenatal PAH exposure and gene 5′-CGI methylation status and for exploratory analyses of PAH exposure status and asthma classification in a larger sample of 56 children from the CCCEH cohort." (PMID 19221603, 2009). "Asthma status did not seem to affect methylation status of ACSL3 promoter." (PMID 19221603, 2009). "First, bisulfite sequencing analyses of an amplicon encompassing the entire predicted ACSL3 5′-CGI (BSPCR marks the amplicon) were performed on the 20 UWBC DNA samples; five from each of the high or low PAH groups with or without asthma." (PMID 19221603, 2009).
hepatocellular carcinoma (13 papers, 2016 to 2026). A malignant tumor that arises from hepatocytes. "LPCAT4 enhanced cell growth and cholesterol biosynthesis by up-regulating ACSL3 in hepatocellular carcinoma (HCC)." (PMID 37294538, 2023). "CPT1A and ACSL3, which are responsible for fatty acid oxidation, have been proved to stimulate gastric cancer and hepatocellular carcinoma cell growth and migration." (PMID 33971821, 2021). "Hepatoma cell models show that ACSL3 is required for the assembly of very low density lipoproteins (VLDLs) while ACSL1 spans a broader plethora of functions, among which are ER, peroxisome and mitochondrial lipid metabolism." (PMID 31344914, 2019). "Furthermore, PPAR-δ is involved in the activation of cytokine oncostatin M-induced ACSL3 expression in hepatoma." (PMID 27171439, 2016). "In hepatocellular carcinoma (HCC), ACSL3 and ACSL4 have been extensively studied, with several studies indicating differential expression of these enzymes in normal liver tissue, metastatic liver lesions, and HCC tissues." (PMID 41288931, 2025). "In hepatocellular carcinoma, IGF2BP3 stabilizes NRF2 mRNA to inhibit ferroptosis; whereas in lung adenocarcinoma, it modulates multiple anti-ferroptotic regulators such as GPX4, SLC3A2, ACSL3, and FTH1 to confer ferroptosis resistance." (PMID 40530014, 2025). "It is reported that in the prognosis model of hepatocellular carcinoma, the genes (NFS1, CISD1, ACSL3, NQO1, SLC7A11, GPX4) that can protect hepatocytes with ferroptosis and the genes (ACACA, CARS, G6PD, SLC1A5) that induce ferroptosis are all up-regulated in HCC, and are related to poor prognosis." (PMID 36387286, 2022). "The expression and subcellular localisations of the ACSL3 and ACSL4 isoforms in hepatocellular carcinoma (HCC), cholangiocarcinoma (CCA) and hepatic metastases were assessed by immunohistochemical analyses of multiple tumour tissue arrays and by subcellular fractionation of cultured HepG2 cells." (PMID 32286604, 2020).
liver cancer (8 papers, 2016 to 2024). An epithelial or non-epithelial malignant neoplasm that arises from the liver. "Consistent with this, analysis using the UALCAN database also confirmed higher mRNA and protein expression of ACSL3 in liver cancer." (PMID 39744125, 2024). "In systematic analysis, ACSL3 was overexpressed in head-neck and liver cancer, but was underexpressed in colorectal cancer." (PMID 27171439, 2016). "The data revealed that the expression level of HAAO in liver cancer is negatively correlated with ferroptosis‐resistant genes including SLC7A11, SLC3A2, and ACSL3, whereas positively correlated with ferroptosis‐sensitive gene ACSL1." (PMID 36627132, 2023). "After evaluating the correlation of these fatty acid‐related genes with the ES cell‐like gene expression signatures in HCC, we found that four genes, including ACSL3, ACSL4, FADS1, and FADS2, were highly related to stem cell characteristics in liver cancer." (PMID 35603967, 2022).